NAPRT (nicotinate phosphoribosyltransferase)
Description:
Catalyzes the first step in the biosynthesis of NAD from nicotinic acid, the ATP-dependent synthesis of beta-nicotinate D-ribonucleotide from nicotinate and 5-phospho-D-ribose 1-phosphate. Helps prevent cellular oxidative stress via its role in NAD biosynthesis.
Synonyms: NAPRT1; PP3856
Tractability: Small molecule: a high-quality ligand is known. Antibody: its Gene Ontology location is reachable by antibodies, with high confidence. PROTAC: ubiquitination databases record sites on it; its protein half-life has been measured; a small molecule that binds it is known.
Target class: Enzyme; Ligase
Gene: Protein-coding gene on chromosome 8 (143,574,782 to 143,578,649, reverse strand). Ensembl gene ENSG00000147813.
Subcellular location: Cytoplasm, cytosol
Subcellular location (Human Protein Atlas): Golgi apparatus; Cytosol; Nucleoplasm
Pathways (Reactome):
Immune System: Neutrophil degranulation
Metabolism: Nicotinate metabolism
Gene Ontology:
Molecular function: nicotinate phosphoribosyltransferase activity; protein binding
Biological process: NAD+ biosynthetic process via the salvage pathway; response to oxidative stress; NAD+ biosynthetic process
Cellular component: cytosol; extracellular exosome; azurophil granule lumen; extracellular region
Genetic constraint (gnomAD): Loss-of-function variants: 67 observed, 55.26 expected, observed/expected ratio (o/e) 1.21, 90% interval 1 to 1.49. The synonymous counts are far from expectation, so gnomAD's model fits this gene poorly and the ratio says little. Missense variants: 818 observed, 685.27 expected, observed/expected ratio (o/e) 1.19, 90% interval 1.13 to 1.26. Synonymous variants: 405 observed, 313.21 expected, observed/expected ratio (o/e) 1.29, 90% interval 1.19 to 1.4.
Homologues: Orthologues: macaque NAPRT (97% identical), chimpanzee NAPRT (96% identical), pig NAPRT (90% identical), dog NAPRT (88% identical), guinea pig NAPRT (85% identical), mouse Naprt (84% identical), rat Naprt (81% identical), zebrafish naprt (55% identical), tropical clawed frog naprt (54% identical), Drosophila melanogaster Naprt (46% identical), Caenorhabditis elegans nprt-1 (43% identical). Paralogues in human: NAMPT (16% identical).
Diseases named in the same sentence as NAPRT in open-access papers:
NAPRT is named in the same sentence as 53 diseases in open-access papers, as found by Europe PMC text mining. Sharing a sentence is not in itself a finding about the gene and the disease. The quoted sentences say what the papers report.
glioma (12 papers, 2019 to 2025). A benign or malignant brain and spinal cord tumor that arises from glial cells (astrocytes, oligodendrocytes, ependymal cells). "For instance, isocitrate dehydrogenase 1 (IDH1)-mutated gliomas typically show diminished NAPRT expression due to NAPRT promoter hypermethylation." (PMID 38396769, 2024). "Overall, these findings demonstrate that PPM1D mutations drive a unique pattern of global DNA methylation, distinct from that found in IDH1 mutant gliomas, which is associated with CpG island hypermethylation and NAPRT gene silencing." (PMID 31439867, 2019). "For example, carcinomas with isocitrate dehydrogenase 1 (IDH1) mutations, such as gliomas and sarcomas, tend to downregulate NAPRT levels through hypermethylation of the NAPRT promoter, thereby blocking the NA–NAPRT pathway, which makes them dependent on NAMPT for NAD replenishment." (PMID 34068917, 2021). "Alternatively, NAPRT silencing makes glioma cells reliant on the nicotinamide phosphoribosyl transferase (NAMPT)-dependent nicotinamide salvage pathway for NAD+ synthesis." (PMID 40565099, 2025). "The NMRGS score of every glioma patient was obtained as follows: NMRGS score = (-0.28992*CD38 expression) + (0.38315*NADK expression) + (-0.04654*NAPRT expression) + (0.2211*NMNAT3 expression) + (-0.24486*PARP6 expression) + (0.29991*PARP9 expression)." (PMID 36845744, 2023). "IDH1-mut glioma cells lowered NAD+ levels by silencing the NAD+ salvage enzyme nicotinic acid phosphoribosyltransferase (NAPRT) and are sensitive to the block of NAD+ biosynthesis via nicotinamide phosphoribosyltransferase (NAMPT) inhibition." (PMID 35267433, 2022). "MutIDH1R132H glioma xenograft cell lines have reduced NAD+ levels as well as lowered nicotinate phosphoribosyltransferase (Naprt1), an enzyme involved in the NAD+ salvagepathway." (PMID 35028610, 2021). "In keeping with this notion, mutations in the protein phosphatase Mg2+/Mn2+-dependent 1D (PPM1D) gene in pediatric gliomas also drive NAPRT gene silencing through the hypermethylation of CpG islands in the NAPRT promoter, thus, again conferring unique sensitivity to NAMPT inhibitors." (PMID 34068917, 2021). "According to the results of qRT-PCR, the mRNA expressions of CD38, NADK, PARP9 were significantly elevated in glioma tissues compared with NBT, while the mRNA expressions of NAPRT and PARP6 showed a significant downward trend in glioma tissues." (PMID 36845744, 2023). "Given that IDH1-mutant cancers are exquisitely reliant on NAMPT for their NAD supplies (as they downregulate NAPRT expression), NAMPT inhibitors were found to exhibit remarkable antitumor activity against IDH1-mutant glioma and fibrosarcoma xenografts." (PMID 34068917, 2021). "We thus conclude that NAPRT is not involved in NAD+ synthesis in gliomas and therefore its downregulation cannot explain the IDH1-related drop in NAD+." (PMID 31888244, 2019).
ovarian carcinoma (12 papers, 2017 to 2025). A malignant neoplasm originating from the surface ovarian epithelium. "In a number of prevalent malignancies, the gene encoding is amplified and overexpressed, including ovarian cancer, where NAPRT expression correlates with the BRCAness gene expression profile." (PMID 36160449, 2022). "On the other hand, Chowdhry and colleagues showed that the inducible depletion of NAPRT caused the regression of OV4 xenografts (PH-amplified ovarian cancer), implying that NAPRT inhibitors might be effective as single agents in similar cancer models that highly depend on the PH pathway to survive." (PMID 35890147, 2022). "Among those two inhibitors, compound 8 was most effective at sensitizing the NAPRT-proficient ovarian cancer cell line OVCAR-5 to FK866." (PMID 40342733, 2025). "In agreement with these insights, the growth of PH-amplified OV4 ovarian cancer xenografts was completely repressed upon NAPRT depletion." (PMID 38396769, 2024). "In epithelial ovarian cancer, it was found that high NAPRT expression was correlated with BRCA gene expression." (PMID 39272943, 2024). "Co-treatment with 2-HNA and FK866 prompted marked cell death of OVCAR-5 (ovarian cancer) and of Capan-1 (pancreatic cancer) cells, which both express NAPRT in abundant amounts (thereby recreating the effects of NAPRT silencing)." (PMID 38396769, 2024). "NAPRT has been shown to have heightened expression in several prevalent cancer types, including ovarian cancer." (PMID 39272943, 2024). "PH-amplified cancers include ovarian cancer, prostate cancer, and pancreatic cancers, which are influenced by the increased expression of NAPRT." (PMID 38116009, 2023). "The docking results were thoroughly inspected and resulted in a selection of 62 compounds to be tested employing in vitro assays on the ovarian cancer cell line OVCAR-5 that expresses high levels of NAPRT." (PMID 35890155, 2022). "Accordingly, we showed that several ovarian cancer cell lines became responsive to FK866 upon NAPRT knock-down both in vitro and in vivo (in mice ovarian cancer xenografts)." (PMID 35890147, 2022). "In a recent work the overexpression of NAPRT in ovarian cancer, correlated with a BRCAness gene expression signature." (PMID 32266141, 2020). "Among this class of compound, 2-hydroxinicotinic acid (2-HNA) is the most promising, showing significant inhibition of NAPRT enzymatic activity and function in ovarian cancer in vitro and in xenograft models." (PMID 32266141, 2020). "The NAPRT gene is overexpressed in a subset of cancer types, including ovarian cancer." (PMID 39272943, 2024). "The first evidence of an anticancer activity attributed to an NAPRT inhibitor was reported by our group in 2017 when we demonstrated that the prototypical NAPRT inhibitor 2-HNA cooperates with FK866 in blunting NAD+ levels in the NAPRT-proficient ovarian cancer OVCAR-5 cells." (PMID 38396769, 2024). "It was then suggested that in cancers with defective HRR, including ovarian cancer, an increase in NAPRT expression confers a selective advantage by ensuring the maintenance of sufficient NAD+ levels, allowing for PARP activity and cellular protection from oxidative stress and DNA damage." (PMID 39272943, 2024). "al. has demonstrated that 90 % of ovarian cancer cell lines are NAPRT positive." (PMID 29100430, 2017). "Due to NAPRT overexpression potentially causing resistance to DNA-damaging agents, the enzyme could act as a possible therapeutic target for patients with BRCA-mutated ovarian cancer to prevent or reverse treatment resistance." (PMID 39272943, 2024). "In cellular models, the two compounds demonstrated anticancer activity at 0.1 mM in cell growth inhibition assays, where the sensitivity of FK866 to NAPRT-expressing ovarian cancer (OVCAR-5 and OVCAR-8) and colorectal cancer (HCT116) cell lines could be restored." (PMID 38396769, 2024).
ovarian carcinoma (continued). "Among the few NAPRT inhibitors, 2-Hydroxynicotinic acid (2-HNA) can sensitize PH-amplified pancreatic and ovarian cancer cells to NAMPT inhibitors." (PMID 38116009, 2023).
pancreatic cancer (10 papers, 2021 to 2025). "Overall, taken together, these results indicate that MAP17 expression correlated with the increased expression of the two most important and limiting enzymes of NAD biosynthesis, NAMPT and NAPRT, which are also upregulated in pancreatic cancer." (PMID 40805270, 2025). "NAMPT and NAPRT levels are significantly increased in pancreatic cancer tumors, and its increased expression correlated with worse prognosis." (PMID 40805270, 2025). "We also demonstrated that NAPRT silencing sensitized NAPRT-proficient ovarian and pancreatic cancer cell lines to FK866 treatment, whereas the NAPRT-proficient wild-type counterparts were completely refractory to NAMPT inhibition." (PMID 38396769, 2024). "We demonstrated that 2-HNA was indeed able to sensitize NAPRT-expressing ovarian and pancreatic cancer cells to NAMPT inhibitors and recapitulated the effect of NAPRT silencing." (PMID 35890147, 2022). "In NAPRT-expressing ovarian and pancreatic cancer cells, 2-HNA recapitulated the effects of NAPRT silencing and sensitized cells to FK866." (PMID 34068917, 2021). "In addition, we found that MAP17 expression positively correlated with NAMPT and NAPRT expressions in different pancreatic cancer databases." (PMID 40805270, 2025). "In ovarian, prostate, breast, and pancreatic cancers, NAPRT was to be found upregulated." (PMID 35890155, 2022). "In preclinical studies, exposure of NAPRT-positive ovarian and pancreatic cancer cells to 2-HNA sensitized them to NAMPT inhibitors and recapitulated the effect of NAPRT silencing." (PMID 40342733, 2025). "High levels of NAPRT and NAMPT have been found in ovarian, prostate and pancreatic cancers, while in glioblastoma, neuroblastoma, chondrosarcoma, leukaemia and gastric and colon cancers, low levels of NAMPT and low levels of NAPRT have been found." (PMID 36078035, 2022). "For instance, we demonstrated that NAPRT-expressing ovarian and pancreatic cancers are resistant to NAMPT inhibition, but downregulation of NAPRT significantly depletes intracellular NAD stores and sensitizes these tumors to NAMPT inhibitors." (PMID 34068917, 2021). "Notably, NAPRT expression is often downregulated in several human cancers with EMT-like features, including gastric cancer (GC) 21, colorectal cancer (CRC), and pancreatic cancer (PAAD)." (PMID 37771778, 2023).
glioblastoma (9 papers, 2016 to 2023). The most malignant astrocytic tumor (WHO grade IV). "A recent study also demonstrated that, although NAPRT is expressed in the majority of healthy tissues, a significant proportion of glioblastomas are NAPRT deficient." (PMID 31888244, 2019). "NAPRT is expressed in the majority of healthy tissues in mammals but a significant proportion of solid tumors, sarcomas, lymphomas, and glioblastomas are NAPRT deficient." (PMID 29100430, 2017). "By causing metabolic stress, inhibition of NAMPT offers a novel therapeutic approach in tumors that lack NAPRT expressions, such as glioblastoma and lymphoma." (PMID 36845744, 2023). "Lack of NAPRT expression in some tumors, such as neuroblastoma or glioblastoma, and lymphomas, places NAPRT as a biomarker for the use of NA as a chemoprotectant agent in the treatment with NAMPT inhibitors." (PMID 26675378, 2016). "The 3C6D2 antibody detects full length NAPRT in most cell lines with the exception of H460 (non-small cell lung), H929 (multiple myeloma), HT1080 (osteosarcoma), U251MG (glioblastoma) and MIA PaCa-2 (pancreatic) cells." (PMID 29100430, 2017). "We previously found that NAD+ restoration in glioblastoma cells utilizes the salvage pathways via NAMPT and NMRK1, while nicotinic acid phosphoribosyltransferase (NAPRT) and de novo synthesis from tryptophan via quinolinic acid phosphoribosyltransferase (QPRT) are not involved." (PMID 35628596, 2022). "It was shown that the lack of NAPRT expression in some tumors, such as neuroblastoma, glioblastoma or lymphomas, puts NAPRT as a biomarker for the use of Na as a chemoprotectant agent during treatment with NAMPT inhibitors." (PMID 32266141, 2020).
colorectal cancer (8 papers, 2016 to 2024). A primary or metastatic malignant neoplasm that affects the colon or rectum. "Second, in some other cancers, such as colorectal cancer, NAMPT and NAPRT high expression are seen to be associated with poor prognosis for the patient." (PMID 36249025, 2022). "Likewise, an inverse relation between the expressions of EMT markers and NAPRT were also seen in pancreatic and colorectal cancer cells." (PMID 38396769, 2024). "To obtain the full-length sequence of the novel NAPRT alternatively spliced transcripts, we amplified the whole coding sequence of three representative human normal tissues, liver, brain and small intestine, and a colorectal carcinoma cell line (HCT-15) and cloned the resulting RT-PCR products." (PMID 26675378, 2016). "To assess NAPRT and NAMPT expression in tumors, we studied a set of cell lines, which included renal, thyroid, cervix, lung, gastric and colorectal carcinomas, uveal melanoma, and leukemia, by RT-PCR and western blot." (PMID 26675378, 2016). "Indeed, overexpression of the enzyme nicotinate phosphoribosyltransferase (NAPRT), which controls the Preiss–Handler pathway, is commonly found in several types of tumors, including ovarian, pancreatic, liver, and colorectal cancers." (PMID 37259338, 2023).
leukemia (7 papers, 2016 to 2025). A malignant (clonal) hematologic disorder, involving hematopoietic stem cells and characterized by the presence of primitive or atypical myeloid or lymphoid cells in the bone marrow and the blood. "On the other hand, in some cell lines such as leukemia ML-2 and HL-60, the full-length transcript was barely detected, although expression of the NAPRT protein was found." (PMID 26675378, 2016). "Importantly, although our data revealed a negative impact of a novel NAD precursor on the anti-leukemic activity of APO866, we also demonstrated that the sensitivity of leukemia cells can be restored by genetically silencing or pharmacologically inhibiting NAPRT." (PMID 36765744, 2023). "Importantly, our data strongly suggest that silencing/inhibition of NAPRT or antibiotic therapy could restore the anti-leukemia efficacy of APO866 despite the presence of bacteria." (PMID 35396381, 2022). "This is consistent with data from lymphoma cell lines and tissue sections indicating that 60-75 % of lymphomas/leukemias are NAPRT negative." (PMID 29100430, 2017). "Also, we found that the NAPRT gene is differentially expressed between cell lines, with a marked decrease in expression in carcinoma cell lines 786-O (renal), MKN28 (gastric), HCT116 (colorectal) and in all leukemia cell lines tested (HL-60, NB4 and ML2)." (PMID 26675378, 2016). "Different from CEM leukemia cells, they do not rely on QPRT as an alternative NAD+-producing enzyme and NAPRT-mediated NAD+ biosynthesis also seems not be involved in their resistance phenotype." (PMID 29541451, 2018).
gastric cancer (6 papers, 2019 to 2025). A primary or metastatic malignant neoplasm involving the stomach. "In these EMT-subtype gastric cancer cell lines, the suppression or loss of NAPRT created a synthetic lethal interaction upon the inhibition of NAMPT, as the cells lacked alternative pathways to produce NAD." (PMID 40282553, 2025). "More recently, selective cytotoxicity of FK866 to mesenchymal gastric cancer cells has also been reported due to loss of NAPRT expression." (PMID 31448236, 2019). "Further evidence was provided by Lee and colleagues who noted that in numerous gastric cancer cell lines, the presence of markers of the epithelial-to-mesenchymal transition (EMT) was associated with a diminished NAPRT expression (again, due to NAPRT-promoter hypermethylation)." (PMID 38396769, 2024). "Furthermore, our previous study revealed NAPRT downregulation as a molecular feature of EMT-subtype gastric cancer cells." (PMID 37771778, 2023). "In light of our previous report demonstrating a strong correlation between NAPRT downregulation and the EMT status of cancer cells in gastric cancer (GC) 21, we investigated whether this trend is conserved in other cancer types." (PMID 37771778, 2023).
neuroblastoma (5 papers, 2016 to 2022). Neuroblastoma (NB) is the most common solid, extracranial childhood tumor. "Neuroblastoma cell lines were assessed for basal expression of N-MYC, NAMPT, as well as nicotinate phosphoribosyltransferase (NAPRT)." (PMID 35814452, 2022).
chondrosarcoma (4 papers, 2021 to 2024). A malignant cartilaginous matrix-producing mesenchymal neoplasm arising from the bone and soft tissue. "Consistently, the methylation of the NAPRT promoter was detected in several chondrosarcoma cell lines and was correlated with a reduced NAPRT expression that, in turn, was associated with enhanced sensitivity to NAMPT inhibitors." (PMID 38396769, 2024).
lung carcinoma (4 papers, 2016 to 2023). "In summary, we identified A4276 as a novel compound with high selectivity for NAPRT-deficient lung cancer cell lines." (PMID 37771778, 2023). "The panel included eight human lung cancer cell lines; three NAPRT-negative and five NAPRT-positive." (PMID 37771778, 2023). "Starting with SW008135, a small-molecule compound whose cytotoxicity is negatively correlated with NAPRT expression as a single biomarker 28, we screened SW008135 derivatives in a panel of lung cancer cell lines with varying NAPRT expression to improve potency and selectivity." (PMID 37771778, 2023). "The lower area under the curve (AUC) and 50% effective dose (ED50) values in NAPRT-negative cell lines demonstrated that A4276 selectively killed NAPRT-deficient lung cancer cell lines." (PMID 37771778, 2023). "Lack of NAPRT expression was observed in several cancer types and associated with NAPRT epigenetic silencing in some cases, such as gastric and lung cancer." (PMID 34946971, 2021). "Even while expressing NAPRT transcripts, thyroid and lung carcinoma cell lines do not show protein expression, suggesting that these are good targets for NA therapy." (PMID 26675378, 2016).
breast carcinoma (3 papers, 2020 to 2024). "It is interesting to note that both desmoplakin, an important constituent of desmosomes, and nicotinate phosphoribosyltransferase, involved in NAD+ biosynthesis, have been linked to breast cancer." (PMID 38928454, 2024).